SNORD49B (small nucleolar RNA, C/D box 49B)
Synonyms: U49B
Gene: Small nucleolar RNA gene on chromosome 17 (16,439,505 to 16,439,576, forward strand). Ensembl gene ENSG00000277108.
Gene Ontology:
Biological process: RNA processing
Cellular component: nucleolus
Homologues: Orthologues: chimpanzee SNORD49B (100% identical), macaque SNORD49B (96% identical), rabbit SNORD49B (81% identical), rat Snord49b (76% identical), mouse Snord49b (72% identical), pig SNORD49B (67% identical). Paralogues in human: SNORD49A (79% identical).
Diseases named in the same sentence as SNORD49B in open-access papers:
SNORD49B is named in the same sentence as 1 disease in open-access papers, as found by Europe PMC text mining. Sharing a sentence is not in itself a finding about the gene and the disease. The quoted sentences say what the papers report.
cancer (1 paper, 2024). A tumor composed of atypical neoplastic, often pleomorphic cells that invade other tissues. "Therefore, we believe that SNORD16, SNORD73B, SCARNA4, and SNORD49B are significant contributors to the development and spread of cancer, even if additional study is required to elucidate their potential molecular pathways." (PMID 38311725, 2024).